RARA (retinoic acid receptor alpha)
Diseases named in the same sentence as RARA in open-access papers (continued):
Sharing a sentence is not in itself a finding about the gene and the disease.
myeloid sarcoma (3 papers, 2021 to 2024). A tumor mass composed of myeloblasts or immature myeloid cells. "While APL patients with PLZF::RARα fusion commonly exhibit diverse hematologic symptoms, the presentation of myeloid sarcoma (MS) as an initial manifestation is infrequent." (PMID 38835381, 2024). "In the present study, we report the clinical features and outcome of a rare APL patient characterized by a cryptic PLZF::RARα fusion and spinal myeloid sarcoma (MS) as the initial presenting symptom." (PMID 38835381, 2024). "A 28-month-old girl with FIP1L1::RARA and complex karyotype was diagnosed with APL complicated by the de novo myeloid sarcoma." (PMID 36776354, 2022).
Non-Alcoholic Steatohepatitis (3 papers, 2022 to 2023). "Regulating the RARα-PPARγ-CD36 cascade can reduce lipid accumulation and lipotoxicity in hepatocytes and reduce nonalcoholic steatohepatitis in mice." (PMID 37755746, 2023).
non-small cell lung carcinoma (3 papers, 2016 to 2025). A group of at least three distinct histological types of lung cancer, including non-small cell squamous cell carcinoma, adenocarcinoma, and large cell carcinoma. "In non-small cell lung cancer (NSCLC) cells, Akt is constitutively active, which is shown to phosphorylate Ser 96 of human RARα, which is conservative in RARs and across species." (PMID 34440929, 2021). "Here, using genetic modulation, transcriptional analysis, and functional studies, we demonstrate a regulatory role for the interaction of the retinoic acid receptor alpha (RARα) and its corepressor, the nuclear receptor corepressor 1 (NCoR1), on CMA in non-small cell lung cancer (NSCLC)." (PMID 40490560, 2025). "A similar result was observed in non-small cell lung cancer with immunohistochemistry, and down-regulation of TRIM24 in head and neck squamous cell carcinoma (HNSCC) cells (WSU-HN6 cells) did not result in high mRNA expression level of RARα." (PMID 27689360, 2016).
oral cancers (3 papers, 2015 to 2020).
Pancytopenia (3 papers, 2012 to 2024). An abnormal reduction in numbers of all blood cell types (red blood cells, white blood cells, and platelets). "The negative lupus panel results and persistent pancytopenia prompted further investigation, leading to the identification of Auer rods in the bone marrow biopsy, PML/RARA translocation, and the subsequent diagnosis of APML." (PMID 39050334, 2024). "Similar risk factors were not present in the presented patient, who had pancytopenia and BCR1-type PML/RARα fusion copies at presentation." (PMID 24744674, 2012). "Moreover, it’s noteworthy that a majority of APL patients harboring the PLZF::RARα fusion initially manifest with non-specific symptoms that were identical to classical APL, including fever, pancytopenia, fatigue, bone pain, and so forth." (PMID 38835381, 2024).
squamous cell carcinoma (3 papers, 2005 to 2023). A carcinoma arising from squamous epithelial cells. "Alterations of retinoic acid receptors (e.g. RARα, β, γ, and RXRα, β, γ) expression is considered to play an important role in development of squamous-cell carcinoma (SCC), which is the most common esophageal cancer." (PMID 16277658, 2005).
triple-negative breast carcinoma (3 papers, 2022 to 2025). An invasive breast carcinoma which is negative for expression of estrogen receptor (ER), progesterone receptor (PR), and human epidermal growth factor receptor 2 (HER2). "Inhibition of DNA methyltransferases (DNMTs) in triple-negative breast cancer cells induced G2/M phase arrest with corresponding suppression in RARA levels." (PMID 35273218, 2022).
asthma (2 papers, 2013 to 2021). "There was concordance of gene over- (STAT1, XBP1) and underexpression (NELF, RARA) in asthma and Crohn’s disease ileum when our results were compared to another dataset (p = 3.66 × 10–7)." (PMID 34332619, 2021).
autism (2 papers, 2021 to 2025). Persistent deficits in social interaction and communication and interaction as well as a markedly restricted repertoire of activity and interest as well as repetitive patterns of behavior. "Our previous studies demonstrated that prenatal VPA exposure induced autism‐like behaviors in offspring by suppressing RA/RARα signaling, downregulating TREM2 expression, and activating microglia." (PMID 41476737, 2025). "Finally, RA supplementation was used to induce RARα signaling and improve autism-like synaptic and behavioral deficits in VPA-exposed offspring." (PMID 33994921, 2021). "Concurrently, we discovered that retinoic acid receptor α (RARα) can bound to the promoter region of the TREM2 gene, regulating its transcription and ameliorating autism‐like behaviors in valproic acid (VPA) model rats." (PMID 41476737, 2025). "After RA supplementation in the VPA-treated offspring, the RA and RARα protein levels were significantly upregulated, GluA1 protein and LTP were downregulated, and most autism-like behavioral deficits were effectively reversed." (PMID 33994921, 2021).
cleft palate (2 papers, 2002 to 2011). Cleft palate is a fissure type embryopathy that affects the soft and hard palate to varying degrees. "In this study, we used mouse embryos harboring null mutations in the genes coding for RALDH3, RARA, or RARG to unravel the possible interaction between atRA and TCDD during palate development and to reassess the etiology of TCDD-induced cleft palate." (PMID 21807577, 2011). "Both TGF and RARA were found to interact with retinoic acid, a recognized teratogen for cleft palate." (PMID 12189550, 2002).
Cognitive impairment (2 papers, 2023 to 2024). Abnormal cognition is characterized by deficits in thinking, reasoning, or remembering. "Most importantly, acitretin, a clinically used RAR agonist, significantly inhibited surgery-induced cognitive impairments and prevented the reduction in RARα and RARα-target genes in the hippocampal regions of aged mice." (PMID 37765280, 2023).
COVID-19 (2 papers, 2022 to 2024). A disease caused by infection with severe acute respiratory syndrome coronavirus 2. "Hence the alteration of retinoic acid receptors (RARs), including RARA and related Retinoid X Receptors (RXRs) including RXRA can facilitate COVID-19 pathogenesis which is evident in the published reports." (PMID 38365632, 2024).
dementia (2 papers, 2020 to 2023). Loss of intellectual abilities interfering with an individual's social and occupational functions. "The link between vitamin A and dementia had been made by Corcoran and colleagues who reported that Rarα was downregulated in the forebrain of 6-month-old vitamin A deficient rats accompanied by a loss of choline acetyltransferase (ChAT) and followed by Aβ deposition in 1-year-old VAD rats." (PMID 31884477, 2020).
depression (2 papers, 2020 to 2025). "RARα was implicated in the activation of HPA axis thus participating in the etiology of depression." (PMID 32040942, 2020). "First, chronic ATRA treatment induced anxiety- and depression-like behaviors in rats, accompanied by upregulated RARα and CRH expression in the hypothalamus." (PMID 40900922, 2025). "Our study demonstrates that chronic ATRA treatment upregulates hypothalamic RARα and CRH, key regulators of the hypothalamic–pituitary–adrenal (HPA) axis, leading to depression-like behaviors in rats." (PMID 40900922, 2025).
endometrial cancer (2 papers, 2024 to 2025). Primary or metastatic malignant neoplasm involving the endometrium (mucous membrane that lines the endometrial cavity). "Results of this study also showed that retinoids may inhibit the cell cycle of endometrial cancer cells by modulating the function of retinoic acid receptor alpha (RAR-α)." (PMID 39337406, 2024).
esophageal cancer (2 papers, 2005 to 2025). A primary or metastatic malignant neoplasm involving the esophagus. "First, it has been demonstrated that RARα was overexpressed in human esophageal carcinoma, whereas silencing RARα expression can attenuate ESCC tumor cell proliferation and metastatic ability through suppressing the Wnt/β-catenin mechanism to resensitize ESCC to chemotherapy treatment." (PMID 40002862, 2025).
histiocytic lymphoma (2 papers, 2016 to 2024). "PR-9 cells were made by stably integrating a Zinc-inducible PML::RARA cDNA into the promonocyte U937 cell line, which was derived from a patient with a histiocytic lymphoma." (PMID 38648485, 2024). "Interestingly, up-regulation of PU.1 levels upon ATRA treatment has been described by Gu and colleagues in U937, a PML/RARA negative histiocytic lymphoma cell line." (PMID 27626703, 2016).
hyperlipidemia (2 papers, 2022 to 2024). "The estrogen signaling pathway was regulated by CA binding to HSP90AA1, MMP2, RARA, PRKACA, ESR1, MMP9, and ESR2 in this present research, which underlies the improvements observed in hyperlipidemia and thrombosis." (PMID 38398534, 2024). "AM580 is a RARα-specific agonist that is already proven to protect from diet-induced hyperlipidemia and hepatic lipid accumulation by inhibiting Apolipoprotein C-III (ApoC-III)." (PMID 36291054, 2022).
Hypermetropia (2 papers, 2009 to 2010). An abnormality of refraction characterized by the ability to see objects in the distance clearly, while objects nearby appear blurry. "Our study represents the first to assess for a genetic association between RARA and myopia, hypermetropia, and ocular biometry." (PMID 19626135, 2009). "This study has found that RARA is not genetically associated with myopia or hypermetropia despite its biological role in the eye." (PMID 19626135, 2009). "Similarly, no variations in the nucleotide sequence of RARα were associated with myopia or hypermetropia, although it was differentially expressed during the development of experimental myopia in guinea pigs and chicks." (PMID 20508731, 2010). "Although our findings do not implicate a direct genetic role for RARA in myopia and hypermetropia, we cannot rule out the possibility that RARA may be just one link in a yet unknown complex pathway involved in causing refractive errors." (PMID 19626135, 2009).
memory impairment (2 papers, 2016 to 2021). "These age-related memory impairments were associated with a hippocampal hypoexpression of RARα, RXRβ, and RXRγ mRNAs in middle-aged control animals." (PMID 27242514, 2016). "Furthermore, we find increases in RARα, FMRP and GluR1 selectively in aged rats with memory impairments." (PMID 34417282, 2021). "Here, we measured plasma RBP4 and protein levels of hippocampal STRA6 receptor, RA synthesizing and catabolizing enzymes, RARα, FMRP, and GluR1 in young (Y) rats and aged animals with and without memory impairment." (PMID 34417282, 2021).
microcephaly (2 papers, 2018 to 2026). A congenital or acquired developmental disorder in which the circumference of the head is smaller than normal for the person's age and sex. "Reduced levels of ECM-related proteins, such as RDH10 and RARA, linked to microcephaly, indicate that ECM dysregulation may contribute to the structural brain abnormalities reported in ALG13-CDG." (PMID 41597222, 2026).
multiple myeloma (2 papers, 2014 to 2021). "We also investigated whether enforced up-regulation of the ATRA receptor, RARα, might make a difference – because RARα2 (not RARα1) is important for myeloma, we used RARα2 for that purpose." (PMID 25230277, 2014). "The activation of NEK2 in myeloma cells relied on the ALDH1A1-dependent generation of the retinoid X receptor α (RXRα) ligand, 9-cis retinoic acid (9CRA) – not the retinoic acid receptor α (RARα) ligand, all-trans retinoic acid (ATRA)." (PMID 25230277, 2014).
myeloproliferative diseases (2 papers, 2021 to 2022). "A 9-month-old boy with a FIP1L1::RARA fusion-associated myelodysplastic/myeloproliferative neoplasm-like overlap syndrome was also reported." (PMID 36776354, 2022).
myopia (2 papers, 2009 to 2010). "In order to further explore the possible role of RARA in the development of refractive errors such as myopia we have undertaken a case-control genetic association study." (PMID 19626135, 2009). "We have utilized a tag single nucleotide polymorphism (tSNP) approach to analyze common polymorphisms within the coding region of RARA and its promoter and assessed for genetic associations to myopia, hypermetropia and ocular biometry measures." (PMID 19626135, 2009). "There is strong evidence from animal studies for a role of RARA and retinoic acid in the development of myopia as well as it having a role in regulating eye length (axial length)." (PMID 19626135, 2009). "The Retinoic Acid Receptor Alpha (RARA) gene is a potential candidate gene for myopia due to its differential expression in animal models during experimentally induced myopia." (PMID 19626135, 2009). "The underlying genes causing refractive errors such as myopia has not been fully elucidated but we hypothesized that the Retinoic Acid Receptor Alpha (RARA) gene represents a plausible candidate." (PMID 19626135, 2009). "Given that changes in retinal gene expression are the likely origin of signals that initiate eye growth it is not unreasonable to hypothesize that RARA may play a role in the development of myopia." (PMID 19626135, 2009).
Nephroblastoma (2 papers, 2017 to 2018). An embryonal neoplasm characterized by the presence of epithelial, mesenchymal, and blastema components. "RARA immunoexpression: A, renal parenchyma; B, nephroblastoma." (PMID 29378601, 2018). "The present work is the first report of the evaluation of RARA and CRABP2 immunoexpression as potential biomarkers and therapeutic targets in nephroblastomas." (PMID 29378601, 2018). "Immunopositivity for RARA and CRABP2 was observed in all three histological components of nephroblastoma (blastema, stroma, and epithelium)." (PMID 29378601, 2018). "The results obtained by quantitative analysis of RARA and CRABP2 expression in the nephroblastoma samples showed median values of 24.2% per HMF (6.3%–40.3%) and 26.3% per HMF (4.2%–40.4%), respectively." (PMID 29378601, 2018). "In conclusion, semiquantitative and quantitative analyses of the markers RARA and CRABP2 indicate these proteins as potential biomarkers of tumor progression and their participation in nephroblastoma tumorigenesis." (PMID 29378601, 2018). "This study aims to evaluate the distribution of RARA and CRABP2 protein expression and positivity in nephroblastoma tissue specimens and to correlate these results with clinical and pathological prognostic factors." (PMID 29378601, 2018). "Semiquantitative and quantitative analyses of the markers RARA and CRABP2 indicate their potential as biomarkers for tumor progression and their participation in nephroblastoma tumorigenesis." (PMID 29378601, 2018). "The aim of this study was to evaluate the immunohistochemical expression of retinoic acid receptor alpha (RARA) and CRABP2 in paraffin-embedded samples of nephroblastomas via semiquantitative and quantitative analyses and to correlate this expression with prognostic factors." (PMID 29378601, 2018).
Parkinson disease (2 papers, 2019 to 2021). A progressive degenerative disorder of the central nervous system characterized by loss of dopamine producing neurons in the substantia nigra and the presence of Lewy bodies in the substantia nigra and locus coeruleus. "Although there is no established agent for modifying CMA activity for clinical application, recent study has shown the potential therapeutic efficacy of specific CMA activation by retinoic acid receptor alpha (RARα) antagonists for mouse model of Parkinson disease." (PMID 34593046, 2021).
psoriasis (2 papers, 2022 to 2023). An autoimmune condition characterized by red, well-delineated plaques with silvery scales that are usually on the extensor surfaces and scalp. "Interestingly, RARA is also targeted by two other retinoids employed in the treatment of severe psoriasis, Tazarotene and Etretinate." (PMID 36437479, 2022).
retinitis pigmentosa (2 papers, 2022 to 2023). Retinitis pigmentosa (RP) is an inherited retinal dystrophy leading to progressive loss of the photoreceptors and retinal pigment epithelium and resulting in blindness usually after several decades. "Recently, modulation of autophagy through selective manipulation of the retinoic acid receptor alpha (RARα) transcriptional program has been shown to increase photoreceptor survival in the retinal degeneration 10 (rd10) mouse model of retinitis pigmentosa." (PMID 37450596, 2023). "Our studies also highlight N-CoR1 as a previously unknown modulator of CMA and link failure of this RARα co-repressor to disease, as exemplified here in the case of retinitis pigmentosa." (PMID 35864098, 2022).
Smith-Magenis syndrome (2 papers, 2014 to 2018). Smith-Magenis syndrome (SMS) is a complex genetic disorder characterized by variable intellectual deficit, sleep disturbance, craniofacial and skeletal anomalies, psychiatric disorders, and speech and motor delay.
steatosis (2 papers, 2023 to 2024). Increased lipid within the cytoplasm of cells. "We also showed in a murine model that treatment with AC261066 limited MASLD, whereas treatment with the RARα agonist AM80 exacerbated steatosis and inflammation." (PMID 37569418, 2023). "Collectively, our data on RARβ and previous research by others on RARα indicate that RARs are protective against steatosis and could be exploited therapeutically to limit the onset of liver disorders characterized by a dysregulation of lipid metabolism." (PMID 37569418, 2023).
varicocele (2 papers, 2021 to 2024). A condition characterized by the dilated tortuous veins of the spermatic cord with a marked left-sided predominance. "In patients with varicocele, it has been shown that RARα expression is significantly reduced, whereas the response to vitamin A treatment is also altered." (PMID 34552778, 2021).
vitamin D deficiency (2 papers, 2024 to 2025). A nutritional condition produced by a deficiency of VITAMIN D in the diet, insufficient production of vitamin D in the skin, inadequate absorption of vitamin D from the diet, or abnormal conversion of vitamin D to its bioactive metabolites. "Several biological mechanisms have been proposed to explain these disparities, including a higher prevalence of vitamin D deficiency, increased aromatase (CYP19) and progesterone receptor-A (PR-A) levels, and reduced retinoic acid receptor-α (RARA) expression in Black women." (PMID 40004152, 2025).
acute megakaryoblastic leukemia (1 paper, 2013). Acute megakaryoblastic leukemia (AMKL) is a form of acute myeloid leukemia (AML) that occurs predominantly in childhood and particularly in children with Down syndrome (DS-AMKL). "In particular, miR-125 overexpression was identified in different AML subtypes characterized by specific chromosomal abnormalities, including AML1/ETO, PML/RARα and FLT3 translocations, and in Down Syndrome-associated acute megakaryoblastic leukemia (AMKL)." (PMID 24145746, 2013).
bone marrow cancer (1 paper, 2023). "Acute promyelocytic leukaemia (APL) is a bone marrow cancer that is characterised by the presence of a chromosomal translocation between the retinoic acid receptor alpha (RARα) gene on chromosome 17 and the promyelocytic leukaemia protein (PML) gene on chromosome 15." (PMID 37446117, 2023).